SLC39A7 (solute carrier family 39 member 7)
Diseases named in the same sentence as SLC39A7 in open-access papers (continued):
Sharing a sentence is not in itself a finding about the gene and the disease.
cancer (31 papers, 2017 to 2025). A tumor composed of atypical neoplastic, often pleomorphic cells that invade other tissues. "Through GSEA analysis, SLC39A7 was associated with several cancer-relative signaling pathways, which promotes cancer process." (PMID 32744318, 2020). "ZIP7 chemical inhibition or SLC39A7 knockdown conferred strong anti-ferroptosis protection, which was abolished by zinc supplementation in human cancer cell lines." (PMID 40227202, 2025). "As a zinc transporter, SLC39A7 plays an important role in activating tyrosine kinase, leading to aggressive and invasive phenotypes of cancer cells." (PMID 32109290, 2020). "SLC39A7 has also been reported to be an important oncogene in several cancers." (PMID 34149917, 2021). "For biological function, high expression of SLC39A7 mainly enhanced multicellular organismal homeostasis, positive regulation of cell-cell adhesion, and maintenance of gastrointestinal epithelium, which may contribute to progress of cancer." (PMID 33535184, 2021). "To gain a better understanding the regulatory mechanism of SLC39A7 in GC, we assessed whether SLC39A7 down-regulation influences the Akt/mTOR signaling pathway which is often aberrantly boosted in various human cancers and affects cell proliferation and apoptosis." (PMID 32109290, 2020). "Knocking down the hub gene SLC39A7, combined with TME scoring, can significantly affect the apoptosis and ferroptosis of cancer cells, with higher prognostic efficacy." (PMID 40009842, 2025). "Then, four zinc transporter genes—ZIP4 (SLC39A4), ZIP6 (SLC39A6), ZIP7 (SLC39A7), and ZIP10 (SLC39A10)—were selected based on their documented roles in cancer-related signalling pathways, such as MAPK, PI3K/AKT, and epithelial-to-mesenchymal transition (EMT)." (PMID 40869403, 2025). "The function of 6 NRGs in our signature, including FASLG, IPMK, FLT3, SLC39A7, HSP90AA1, and LEF1, are studied in various cancer types, including BC." (PMID 35864548, 2022). "As a zinc transporter, SLC39A7 (zip7) is vital in intestinal epithelial self-renewal, and recent studies suggested that SLC39A7 was related to cancer progression." (PMID 32109290, 2020). "qRT-PCR was employed to analyze SLC39A7 mRNA expression in cancer tissues and matched adjacent non-tumor tissues from 36 GC patients as well as GC cell lines and normal cell lines." (PMID 32109290, 2020).
tumor (16 papers, 2017 to 2025). "Our findings suggested that higher expressed SLC39A7 was associated with more serious tumor size and metastasis, which were consistent with the in vitro experiments." (PMID 32744318, 2020). "Besides, SLC39A7 is demonstrated to regulate zinc-mediated tyrosine kinase signaling, which might make it to be positively associated with tumor progression." (PMID 32109290, 2020). "Beyond ZIP10, other ZIPs contribute to tumorigenesis: SLC39A1 is upregulated in gastric adenocarcinoma and acts as an oncogene by promoting tumor growth and metastasis, whereas upregulated SLC39A7 promotes cell growth and survival through the Akt/mTOR pathway." (PMID 41583444, 2025). "The results demonstrated that SLC39A7 was obviously higher expressed in tissues of GC patients than that of non-tumor tissues." (PMID 32109290, 2020). "The protein level of SLC39A7 was significant higher in primary tumor tissue of BC than in normal tissues." (PMID 32744318, 2020). "In the TCGA database, the expression levels of HAT1 and SLC39A7 in tumor tissues were higher than those in adjacent normal tissues, while the expression level of MYC in tumor tissues was lower than that in adjacent normal tissues." (PMID 37000317, 2023). "Knockdown of SLC39A7 in T98G significantly extended the MST of nude mice to 39 and 40 days (MST, control group = 29 days), which was consistent with the significant smaller tumor volumes observed in the SLC39A7 knockdown group compared with the control group." (PMID 34149917, 2021). "The expression of SLC39A7 was significantly higher in tumor tissues than which in normal lung tissue." (PMID 33535184, 2021).
infection (2 papers, 2020 to 2021). The state of being infected such as from the introduction of a foreign agent such as serum, vaccine, antigenic substance or organism. "To evaluate the role of SLC39A7 in the host response to BCG-p infection we examined the phagocytic capacity of SLC39A7 knockdown cells and non-targeting control (NC)." (PMID 32645059, 2020). "Western blotting and quantitative PCR were performed to detect the expression of SLC39A7 after infection at 6h and 24h." (PMID 32645059, 2020). "We first determined whether expression of SLC39A7 was regulated in macrophages during infection of BCG Pasteur stain (BCG-p)." (PMID 32645059, 2020). "To evaluate the function of SLC39A7 during infection in macrophages, we used the CRISPR-Cas9 gene editing system to generate SLC39A7-knockdown cell lines." (PMID 32645059, 2020).
autosomal recessive disease (1 paper, 2022). Autosomal recessive form of disease. "In the SLC39A7 knockdown mice, the remaining B-cells, exhibit reduced cytoplasmic Zn contents, similar to patients suffering from a recently discovered autosomal recessive disease caused by hypomorphic mutations of SLC39A7." (PMID 35745255, 2022).
genetic diseases (1 paper, 2019). "It is therefore tempting to speculate that loss-of-function or hypomorphic mutations in SLC39A7 may result in associated genetic diseases." (PMID 30237509, 2019).
SLC39A7 also shares sentences with these, for which no sentence is quoted: Zinc deficiency (6 papers); Insulin resistance (5); osteosarcoma (4); Hyperglycemia (3); neurodegenerative disease (3); breast tumors (2); Immunodeficiency (2); liver cancer (2); lung carcinoma (2); lung squamous cell carcinoma (2); Alzheimer disease (1); autoimmune lymphoproliferative syndrome (1); cardiac diseases (1); cardiovascular diseases (1); CLN6 disease (1); cognitive decline (1); Cognitive impairment (1); colon cancers (1); connective tissue disorder (1); gastric adenocarcinoma (1); gastrointestinal disorders (1); gastrointestinal tumors (1); heart failure (1); hepatocellular carcinoma (1); keloid (1); kidney damage (1); leukemia (1); lung fibrosis (1); metastatic disease (1); myeloid leukaemia (1).
A further 9 diseases each share a sentence with SLC39A7 in 1 paper.